TFAM (transcription factor A, mitochondrial)
Diseases named in the same sentence as TFAM in open-access papers (continued):
Sharing a sentence is not in itself a finding about the gene and the disease.
aneurysm (3 papers, 2021 to 2025). Bulging or ballooning in an area of an artery secondary to arterial wall weakening. "Moreover, loss of TFAM expression appears to be causative of aneurysm formation, as conditional TFAM-deficient VSMC mice lose their VSMC contractile capacity, develop aortic aneurysm formation, and die prematurely." (PMID 37175915, 2023). "Next, we tried to elucidate how aneurysms caused by mutations related to ECM and VSMC contractile function converge on the impairment of TFAM expression and mitochondrial dysfunction." (PMID 33709773, 2021).
asthma (3 papers, 2011 to 2024). "Among the genes regulated by TFAM at the alternative splicing levels, some have been reported to be associated with asthma." (PMID 34876009, 2021). "Previous studies show that TFAM is associated with inflammatory diseases, such as neurodegenerative diseases and asthma." (PMID 34876009, 2021). "Mitochondrial transcription factor A (TFAM) is associated with a number of neurodegenerative diseases and also with asthma." (PMID 34876009, 2021). "Research has shown that mtDNA content, mtDNAcn, and the mitochondrial transcription factor A (TFAM) —a key regulator of mtDNA—are reduced in the lung tissue of mice subjected to an asthma model and exposed to e-cigarettes smoke." (PMID 39382744, 2024). "To explore the potential regulatory mechanisms of TFAM in asthma, we conducted the RNA-seq based on TFAM overexpression and control in vitro." (PMID 34876009, 2021). "Nevertheless, the role of TFAM in asthma related inflammation remains obscure." (PMID 34876009, 2021). "Thus, we overexpressed TFAM in A549 cells to get the transcriptional profiles to research the mechanism in asthma in vitro." (PMID 34876009, 2021). "TFAM has been reported to be participate in the asthma development by BSM, while functions of TFAM in lung epithelial cells unknown." (PMID 34876009, 2021). "This interplay between TFAM and arginine metabolism may coordinately contribute to the pathology of asthma." (PMID 34876009, 2021). "The purpose of this study was to investigate the regulatory mechanism of TFAM in asthma." (PMID 34876009, 2021). "However, the role of TFAM in asthma related inflammation remains obscure." (PMID 34876009, 2021).
Atrophy (3 papers, 2018 to 2026). Any weakening or degeneration, especially through lack of use. "TFAM has linked to muscle atrophy, and animal study suggested a combination of exercise and TFAM leads to an interactive effect in targeting mitochondrial function to prevent skeletal muscle atrophy." (PMID 36293409, 2022). "Based on this evidence, exercise was chosen as a preconditioning treatment to prevent disuse-associated atrophy because of the well-known inducing effect it has on mitochondrial biogenesis, particularly PGC-1α and TFAM, and mitochondrial function." (PMID 29975600, 2018). "However, unlike in Dex‐treated mice, PSE did not affect HFHS‐mediated lowered grip strength (forelimb + hindlimb) and hanging capacity with PGC1α and TFAM protein expression (data not shown), suggesting that TFAM induction by PSE may be specific to Dex‐induced atrophy." (PMID 41567165, 2026).
brain injury (3 papers, 2021 to 2023). Acute and chronic (see also brain INJURIES, CHRONIC) injuries to the brain, including the cerebral hemispheres, CEREBELLUM, and brain STEM. "At the same time, Res can stimulate mitochondrial biogenesis through the PGC-1α/Nrf/TFAM/mtDNA signalling pathway, increase the number of mitochondria in nerve cells, and thus have a protective effect on hyperoxia-induced brain injury in neonatal pups." (PMID 37098490, 2023). "Previous studies reported that neural mitochondrial biogenesis regulators (e.g., PGC-1α, TFAM, NRF-1, and NRF-2) were upregulated as a compensatory response to energy demand and reductions in neural mitochondrial content in I/R-induced brain injury." (PMID 35002619, 2021).
cognitive decline (3 papers, 2016 to 2025). "Moreover, targeted deletion of mitochondrial transcription factor A (TFAM) exacerbates T cell senescence, precipitating metabolic dysregulation, cognitive decline, and premature mortality." (PMID 41299782, 2025). "Furthermore both PGC-1α and TFAM well correlated with cognitive decline." (PMID 26881032, 2016). "Experimental T-cell-specific deletion of the mitochondrial transcription factor A (TFAM) in mice resulted in an extremely differentiated TH1 phenotype, premature inflammation, cognitive decline, and a reduction in lifespans by 50%." (PMID 39408862, 2024).
COVID-19 (3 papers, 2022 to 2024). A disease caused by infection with severe acute respiratory syndrome coronavirus 2. "Inhibition of TFAM in COVID-19 patients is not just limited to the transcriptional level." (PMID 35409008, 2022).
diabetic nephropathy (3 papers, 2023 to 2025). "Consistently, inhibition of AMPK or Sirt1 or downregulation of PGC-1α with a siRNA significantly reduced ATP production and downregulated the expression of mitochondrial biogenesis markers such as Nrf-1 and mitochondrial factor A (TFAM) in a mouse model of diabetic nephropathy." (PMID 36818747, 2023). "TFAM protects mitochondrial DNA integrity in diabetic nephropathy." (PMID 36818747, 2023). "Supporting evidence from diabetic nephropathy models suggests that AS-IV can enhance mitochondrial function and mitigate oxidative damage by upregulating the Nrf2-ARE/TFAM signaling pathway, potentially indicating mechanistic parallels in PF." (PMID 40822469, 2025).
ischemia (3 papers, 2021 to 2025). A hypoperfusion of the BLOOD through an organ or tissue caused by a PATHOLOGIC CONSTRICTION or obstruction of its BLOOD VESSELS, or an absence of BLOOD CIRCULATION. "Meanwhile, the decline of PGC1-α expression, a vital regulator in mitochondrial biogenesis, and its downstream target mitochondrial transcription factor A (TFAM) both impair mitochondrial biogenesis under ischemia and hypoxia conditions, causing functional deterioration following cerebral IRI." (PMID 34745418, 2021). "When ischemia occurs, the accumulation of reactive oxygen species (ROS) in the body hinders the transfer mitochondrial transcription factor A (TFAM) mRNA transcription and facilitates the release of TFAM and mitochondrial DNA (mtDNA) into the cytosol." (PMID 40165854, 2025). "mSC-EVS has been shown to reduce mtDNA damage and inflammation after AKI in an ischemia-reperfusion–induced AKI model, which is dependent on the mitochondrial transcription factor A (TFAM) pathway." (PMID 36248840, 2022).
lipid metabolism disorder (3 papers, 2021 to 2026). "The improvement of lipid metabolism disorder may occur through increasing liver mitochondrial biosynthesis-related genes (PGC-1α and TFAM) and restoring mitochondrial dynamics-related gene (MFN2 and DRP1) mRNA levels." (PMID 36676939, 2022).
Marfan syndrome (3 papers, 2022 to 2025). A disorder of the connective tissue. "Patients with Marfan syndrome develop aortic aneurysms and have decreased TFAM expression and mtDNA levels in aortas." (PMID 37175915, 2023). "Restoration of mitochondrial metabolism with the NAD precursor nicotinamide riboside (NR) rapidly reduced aortic aneurysm formation in Marfan syndrome mice and in the AngII-infused model in ApoE−/− mice fed with a western diet, increasing the expression of PGC-1α and TFAM." (PMID 37175915, 2023). "Transcriptomics studies in aortas from Marfan syndrome mouse models (Fbn1C10341G/+) and multi-omics approaches in human aortas from MFS patients have consistently revealed significant reductions in key regulators of mitochondrial function, including PGC1α, TFAM, and mitochondrial complexes." (PMID 40277943, 2025).
Mitochondrial myopathy (3 papers, 2017 to 2024). "Second, there are a few animal models for studying mitochondrial myopathy, neurodegenerative diseases or apoptosis by disrupting the gene for TFAM." (PMID 28465355, 2017).
myocardial ischemia (3 papers, 2018 to 2021). A disorder of cardiac function caused by insufficient blood flow to the muscle tissue of the heart. "Taken together, our results indicated that KLF16 suppressed TFAM expression, leading to oxidative stress and inflammation in model of myocardial ischemia-reperfusion." (PMID 34823421, 2021). "Collectively, these data indicated that KLF16 reduced oxidative stress and inflammation to present myocardial ischemia-reperfusion by TFAM/PPARβ signal passage." (PMID 34823421, 2021). "In conclusion, the results from this study demonstrate that KLF16 reduced oxidative stress and inflammation, and presented MI in vivo model of myocardial ischemia-reperfusion through the induction of PPARβ by TFAM." (PMID 34823421, 2021). "Here, we showed TFAM/PPARβ signal passage is target spot of KLF16 in Myocardial ischemia-reperfusion." (PMID 34823421, 2021). "Apart from that, the down-regulation of KLF16 suppressed PPARβ and KLF16 protein expressions, and induced TFAM protein expression in vitro model of myocardial ischemia-reperfusion." (PMID 34823421, 2021). "Meanwhile, over-expression of KLF16 not only induced PPARβ and KLF16 protein expressions, but also suppressed TFAM protein expression in vitro model of myocardial ischemia-reperfusion." (PMID 34823421, 2021). "Anti-KLF16 body suppressed PPARβ protein expression and induced TFAM protein expression in heart tissue of mice with myocardial ischemia-reperfusion." (PMID 34823421, 2021). "Immunofluorescence showed that the over-expression of KLF16 suppressed TFAM expression in vitro model of myocardial ischemia-reperfusion." (PMID 34823421, 2021). "The assessed the role of TFAM involved in the function of KLF16 in myocardial ischemia-reperfusion by interacting with its promoter." (PMID 34823421, 2021). "Human KLF16 recombinant protein induced PPARβ protein expression, and suppressed TFAM protein expression in heart tissue of mice with myocardial ischemia-reperfusion." (PMID 34823421, 2021). "We found that QSG could promote the mitochondrial function and antioxidant response via the PGC-1α/NRF1/TFAM pathway to alleviate the effects of myocardial ischemia on mitochondrial dysfunction and oxidative stress in myocardial cells." (PMID 35003305, 2021). "TFAM participate in KLF16 affects myocardial ischemia-reperfusion." (PMID 34823421, 2021). "The study further assessed that the role of TFAM in KLF16 affects myocardial ischemia-reperfusion." (PMID 34823421, 2021). "Serum mRNA of KLF16 was negative correlation with serum TFAM mRNA expression in patients with myocardial ischemia-reperfusion." (PMID 34823421, 2021). "KLF16 plays a key role in the maintenance of myocardial ischemia-reperfusion and KLF16 may alleviate oxidative stress and inflammation by activation of TFAM/PPARβ signaling pathway." (PMID 34823421, 2021). "The current study showed that TFAM interlink KLF16 in Myocardial ischemia-reperfusion, and KLF16 induced PPARβ protein expressions, and suppressed TFAM protein expression in vivo and vitro model of myocardial ischemia-reperfusion." (PMID 34823421, 2021). "For example, in contrast to our results, in a non-cancerous model of myocardial ischemia/reperfusion injury in type 1 diabetic rats, melatonin has increased TFAM expression, reducing mitochondrial oxidative stress and enhancing its biogenesis." (PMID 29747444, 2018).
neuroblastoma (3 papers, 2015 to 2023). Neuroblastoma (NB) is the most common solid, extracranial childhood tumor. "First, we analyzed the effect of C/EBPβ overexpression in TFAM levels in the mouse N2A neuroblastoma cell line and in the previously generated p4 pool stably transfected with a pcDNA3-C/EBPβ expression plasmid." (PMID 36674978, 2023). "When used as a pretreatment, curcumin prevents Aβ-induced toxicity in the human SH-SY5Y neuroblastoma cell line by increasing mRNA and protein levels of mitochondrial genes, such as nuclear respiratory factor 1 (Nrf1) and mitochondrial transcription factor A (TFAM)." (PMID 33217959, 2020).
osteoporosis (3 papers, 2016 to 2022). A condition of reduced bone mass, with decreased cortical thickness and a decrease in the number and size of the trabeculae of cancellous bone (but normal chemical composition), resulting in increased fracture incidence. "There is further evidence for potential mitochondrial involvement in osteoporosis, for example in mice with mitochondrial transcription factor A (TFAM) deficient osteoclasts, increased resorption is observed, tipping the net balance in favour of bone resorption rather than formation." (PMID 27553587, 2016). "A study demonstrated that mitochondrial dysfunction is a potent contributor to osteoporosis where a specific knockout of mitochondrial transcription factor A (TFAM) in osteoclasts increases bone resorption in comparison to wild-type cells." (PMID 36497201, 2022).
serous ovarian cancer (3 papers, 2015 to 2025). "PGC1α and mitochondrial transcription factor A (TFAM) were found to be increased in high grade serous ovarian cancers that were highly chemoresistant." (PMID 28947972, 2017). "First, analysis of EOC RNA-seq data (GSE209964) from the GEO database showed that the mitochondrial genes TFAM, HSPE1, and CYC1 were significantly upregulated in high-grade serous ovarian cancer." (PMID 39927160, 2025).
alcoholic cirrhosis (2 papers, 2014 to 2024). "In addition, it has been shown that TFAM expression in hepatocytes is significantly reduced and mitochondrial function is dysfunctional during the pathogenesis of alcoholic cirrhosis, while hepatocyte-specific TFAM overexpression prevents alcohol-induced mitochondrial dysfunction in mice." (PMID 39701936, 2024).
anemia (2 papers, 2023 to 2024). A reduction in the number of red blood cells, the amount of hemoglobin, and/or the volume of packed red blood cells. "Although modest compared to the effect of TFAM and PHB2 expression, the data suggest an upregulation of mitophagy in ribosome insufficiency also contributes to reduced mitochondrial biogenesis and anemia." (PMID 38992436, 2024).
autoimmune disease (2 papers, 2013 to 2016). A disorder resulting from loss of function or tissue destruction of an organ or multiple organs, arising from humoral or cellular immune responses of the individual to their own tissue constituents. "Although these findings may preclude the use of TFAM as a CpG-B enhancing vaccine adjuvant, TFAM may be useful for decreasing the pathogenic consequences of exposure to hypomethylated DNA in the context of trauma, autoimmune disease, or infection." (PMID 27280778, 2016). "Thus, TFAM has the potential to decrease the pathogenic consequences of exposure to natural CpG-like hypomethylated DNA in vivo, as well as such as that found in traumatic injury, infection, autoimmune disease and during pregnancy." (PMID 27280778, 2016). "TFAM has been shown to bind DNA with nanomolar affinity, and could potentially shed light on novel treatments for autoimmune diseases such as lupus where self DNA creates unwanted activation of TLR9 receptors." (PMID 27280778, 2016). "As such, this study suggests that pDC responses to TFAM and mtDNA, which are released in the setting of cell damage, could be critical for the regulation of sterile immune responses in the setting of inflammatory and autoimmune diseases." (PMID 23951313, 2013).
brain tumor (2 papers, 2018 to 2024). "The research aimed to explore the specific contributions of mtDNA copy number changes and their correlations with patient survival, large mtDNA deletions, and TFAM mutations in brain tumor patients." (PMID 39128073, 2024).
cervical cancer (2 papers, 2022 to 2023). A primary or metastatic malignant neoplasm involving the cervix. "For example, in cervical cancer, patients with TFAM rs3900887 TT and TA genotypes had a lower risk of larger tumors than patients with the AA genotype." (PMID 36833361, 2023).
cholestasis (2 papers, 2024). Impairment of the bile flow caused by obstruction within the liver, or outside the liver in the bile duct system. "Here, we describe a novel case of TFAM mutation presenting with progressive neonatal cholestasis, hypoglycemia and abnormal amino acid profiling." (PMID 39716297, 2024).
chronic kidney disease (2 papers, 2022 to 2025). Impairment of the renal function secondary to chronic kidney damage persisting for three or more months. "In vivo, increasing muscle mitochondrial biogenesis via TFAM‐OE can reprogram EV secretion, with altered contents in injured muscle tissues of chronic kidney disease (CKD) mice." (PMID 40162496, 2025). "Notably, specific deletion of Tfam in renal tubule cells develops metabolic dysfunction and severe renal disease in mice, which models the decreased TFAM expression observed in the kidney of patients with chronic kidney disease." (PMID 35084490, 2022).
Cirrhosis (2 papers, 2023 to 2025). A chronic disorder of the liver in which liver tissue becomes scarred and is partially replaced by regenerative nodules and fibrotic tissue resulting in loss of liver function. "Analyses of expression data in GSE14323 showed increased expression of ZNF281 in HCC compared with normal and cirrhosis liver tissues but decreased expression of PGC-1α, TFAM, TFB1M, and TFB2M." (PMID 37880213, 2023).
clear cell carcinoma (2 papers, 2014 to 2022). "Contradicting these observations, other studies showed that HGSCs exhibited higher expression of PGC-1α/TFAM compared to clear cell carcinoma, which was related to better prognosis and chemosensitivity to initial platin and taxane therapy." (PMID 36012230, 2022). "Here, we report for the first time that the expression of the mitochondrial regulators PGC1α and TFAM varies between EOC subtypes; furthermore, we have identified a profile in clear-cell carcinoma consisting of undetectability of PGC1α/TFAM, and low ERα/Ki-67." (PMID 25243473, 2014).
colon adenocarcinoma (2 papers, 2016 to 2021). "For example, one study showed that the expression of TFAM is frequently upregulated in colon adenocarcinoma tissues compared with the corresponding paracancerous tissues." (PMID 34235078, 2021). "TFAM expression was also observed to be significantly higher in colon adenocarcinoma tissues than in paracancerous tissues (p = 0.01)." (PMID 27732955, 2016). "In our study, high TFAM expression was revealed in the TMA of patients with colon adenocarcinoma, which was correlated to advanced TNM stage, high incidence of positive lymph nodes, a low 5-year survival rate and poor prognosis." (PMID 27732955, 2016).
emphysema (2 papers, 2018 to 2022). "Mitochondrial copy number and TFAM expression levels are reduced in the lungs of COPD/emphysema patients." (PMID 35384838, 2022). "Lungs from emphysema patients exhibit a reduction in mitochondrial DNA and TFAM expression." (PMID 35384838, 2022). "In addition, TFAM protein levels were reduced in lysates from emphysema lungs compared to normal lungs." (PMID 35384838, 2022).